KLKP1 (kallikrein pseudogene 1)
Synonyms: KLK31P; YKLK1; PsiKLK1
Gene: Transcribed unprocessed pseudogene on chromosome 19 (50,887,866 to 50,888,268, reverse strand). Ensembl gene ENSG00000197588.
Subcellular location: Cytoplasm; Nucleus
Diseases named in the same sentence as KLKP1 in open-access papers:
KLKP1 is named in the same sentence as 1 disease in open-access papers, as found by Europe PMC text mining. Sharing a sentence is not in itself a finding about the gene and the disease. The quoted sentences say what the papers report.
prostate carcinoma (3 papers, 2012 to 2021). A carcinoma that arises from epithelial cells of the prostate gland. "The unique feature of the KLK4-KLKP1 fusion gene is the conversion of the non-coding KLKP1 pseudogene into the gene encoding the protein and its unique expression in about 30% of high-grade Gleason prostate cancer." (PMID 34947885, 2021). "Expression analysis of KLK4, KLK4T2, and KLKP1 transcripts in prostate cancer cell lines showed high levels of KLKP1 transcripts in the nucleus and in unfractionated cell extract, whereas it was almost completely absent in the cytoplasmatic fraction." (PMID 34884832, 2021). "The closest validated gene to the KLK4 3′ end is the Kallikrein family pseudogene KLKP1, thus these SNPs may regulate the activity of this pseudogene or expression of KLKP1 transcripts, which have been shown to be down-regulated in prostate cancer tissues." (PMID 22970239, 2012).